LAMB2 (laminin subunit beta 2)
Description:
Binding to cells via a high affinity receptor, laminin is thought to mediate the attachment, migration and organization of cells into tissues during embryonic development by interacting with other extracellular matrix components.
Synonyms: LAMS; NPHS5; PIERS
Tractability: Antibody: its Gene Ontology location is reachable by antibodies, with high confidence; UniProt places it where antibodies can reach, with medium confidence; UniProt predicts a signal peptide or a membrane-spanning region. PROTAC: ubiquitination databases record sites on it; its protein half-life has been measured. Other modalities: an approved drug acts on it.
Gene: Protein-coding gene on chromosome 3 (49,121,113 to 49,133,118, reverse strand). Ensembl gene ENSG00000172037.
Subcellular location: Secreted, extracellular space, extracellular matrix, basement membrane
Subcellular location (Human Protein Atlas): Vesicles; Cytosol; Predicted to be secreted
Pathways (Reactome):
Extracellular matrix organization: ECM proteoglycans; Formation of the dystrophin-glycoprotein complex (DGC); Laminin interactions; Non-integrin membrane-ECM interactions
Metabolism of proteins: Post-translational protein phosphorylation; Regulation of Insulin-like Growth Factor (IGF) transport and uptake by Insulin-like Growth Factor Binding Proteins (IGFBPs)
Developmental Biology: Developmental Lineage of Pancreatic Ductal Cells
Disease: Attachment of bacteria to epithelial cells
Signal Transduction: MET activates PTK2 signaling
Gene Ontology:
Molecular function: protein binding; extracellular matrix structural constituent; structural molecule activity; integrin binding; structural constituent of synapse-associated extracellular matrix
Biological process: positive regulation of cell adhesion; positive regulation of integrin-mediated signaling pathway; positive regulation of muscle cell differentiation; regulation of basement membrane organization; substrate adhesion-dependent cell spreading
Cellular component: basement membrane; extracellular exosome; extracellular matrix; laminin-3 complex; endoplasmic reticulum lumen; extracellular region; laminin-11 complex; laminin-14 complex; laminin-15 complex; laminin-4 complex; laminin-522 complex; laminin-7 complex; laminin-9 complex; protein complex involved in cell-matrix adhesion; laminin complex; neuromuscular junction; synapse; synaptic cleft
Genetic constraint (gnomAD): Loss-of-function variants: 119 observed, 212.57 expected, observed/expected ratio (o/e) 0.56, 90% interval 0.48 to 0.65. The upper end of that interval is the gene's LOEUF score, 0.65, which puts it in group 2 of 6, group 1 being the genes least tolerant of losing a copy. Missense variants: 2,124 observed, 2,518.5 expected, observed/expected ratio (o/e) 0.84, 90% interval 0.81 to 0.87. Synonymous variants: 818 observed, 948.82 expected, observed/expected ratio (o/e) 0.86, 90% interval 0.81 to 0.91.
Homologues: Orthologues: chimpanzee LAMB2 (99% identical), macaque LAMB2 (96% identical), rabbit LAMB2 (92% identical), dog LAMB2 (91% identical), pig LAMB2 (91% identical), mouse Lamb2 (88% identical), rat Lamb2 (88% identical), guinea pig LAMB2 (88% identical), zebrafish lamb2 (59% identical), tropical clawed frog XB5969698 (51% identical). Paralogues in human: LAMB1 (50% identical), LAMB4 (38% identical), LAMA5 (23% identical), LAMA2 (23% identical), LAMA1 (23% identical), LAMB3 (22% identical), LAMA3 (22% identical), LAMC1 (21% identical), LAMC3 (21% identical), USH2A (19% identical), HSPG2 (17% identical), AGRN (15% identical), and 15 more.
Diseases named in the same sentence as LAMB2 in open-access papers:
LAMB2 is named in the same sentence as 80 diseases in open-access papers, as found by Europe PMC text mining. Sharing a sentence is not in itself a finding about the gene and the disease. The quoted sentences say what the papers report.
Pierson syndrome (34 papers, 2006 to 2025). Pierson syndrome is characterized by the association of congenital nephrotic syndrome and ocular anomalies with microcoria. "Homozygous or compound heterozygous variants in the LAMB2 gene are associated with Pierson syndrome, defined by congenital nephrotic syndrome and ocular and neuromuscular abnormalities." (PMID 40003707, 2025). "LAMB2 mutations are implicated in Pierson syndrome, a rare disorder commonly involving neurodevelopmental impacts." (PMID 39882510, 2025). "LAMB2 mutations cause both the more severe disease, Pierson syndrome, as well as nephrotic syndrome type 5." (PMID 37578539, 2024). "Pierson syndrome (OMIM 609049) is an autosomal recessive disorder secondary to variants in LAMB2 and is characterized by CNS, neurodevelopment abnormalities and eyes anomalies including microcoria and hypoplasia of the ciliary and pupillary muscles." (PMID 37204080, 2023). "Two reported patients with Pierson syndrome caused by LAMB2 variants exhibited distinct retinal manifestations, including one with retinal atrophy change and one with retinal detachment, following early-onset renal failure." (PMID 37711606, 2023). "The LAMB2 gene is the causative gene of Pierson syndrome (OMIM #609049), with which the majority of patients died early and the survivors presented severe neurodevelopmental delays." (PMID 35663266, 2022). "Pierson syndrome first described in 1963, is a severe congenital nephrotic syndrome with eye abnormalities, caused by mutations in LAMB2 (LMβ2)." (PMID 34456976, 2021). "Both Pierson syndrome (PS) and isolated nephrotic syndrome can be caused by LAMB2 biallelic pathogenic variants." (PMID 33982833, 2021). "Mutations in the laminin β2 gene (LAMB2) cause Pierson syndrome, which is characterized by congenital nephrotic syndrome with severe ocular and neuromuscular defects." (PMID 33749661, 2021). "The present results suggest a novel mechanism underlying isolated nephropathy caused by LAMB2 defects, which is clinically and genetically distinct from Pierson syndrome." (PMID 33749661, 2021). "Recessive mutations in LAMB2 can cause either Pierson syndrome (PS, OMIM: #609049) or isolated nephrotic syndrome with onset in the first year of life (OMIM: #614199)." (PMID 33982833, 2021). "On the other hand, the patients with LAMB2 missense mutations occasionally exhibit higher mean age at onset of renal disease or oligosymptomatic disease variants of Pierson syndrome." (PMID 33749661, 2021). "Among syndromic forms, WT1-associated glomerulopathy is the most frequent, followed by Pierson syndrome caused by LAMB2 biallelic pathogenic variants." (PMID 32467597, 2020). "Here we report the first Uyghur patient with typical Pierson syndrome phenotypes and a novel pathogenic homozygous variant in LAMB2 gene." (PMID 30778388, 2019). "LAMB2 encodes laminin β2 and its mutations cause Pierson syndrome (congenital nephrotic syndrome-microcoria syndrome)." (PMID 29594119, 2018). "Pierson syndrome (PS) is a rare autosomal recessive disorder, caused by mutations in the laminin β2 (LAMB2) gene." (PMID 27130041, 2016). "LAMB2 mutations cause Pierson syndrome (OMIM 609049), an autosomal recessive genetic disease typically characterized by congenital nephrotic syndrome (CNS) and early onset renal failure, as well as bilateral microcoria." (PMID 27004562, 2016). "Pierson syndrome was confirmed, with a novel homozygous nonsense mutation c.2890C>T (p.R964*) in the LAMB2 gene." (PMID 27130041, 2016). "We here describe a novel nonsense homozygous mutation in LAMB2 gene causing a severe neonatal presentation of Pierson syndrome." (PMID 27130041, 2016). "LAMB2 (MIM# 150325) mutation typically causes Pierson syndrome (OMIM 609049), an autosomal recessive disease presenting as congenital nephrotic syndrome (CNS) and early onset renal failure, as well as bilateral microcoria." (PMID 27004562, 2016).
Pierson syndrome (continued). "Mutations in LAMB2 cause Pierson syndrome (OMIM 609049), which is characterized by CNS/diffuse mesangial sclerosis, severe ocular abnormalities, and neurodevelopmental impairments." (PMID 26156092, 2015). "Although LAMB2 null mutations cause the full syndromic phenotype of Pierson syndrome, certain LAMB2 missense mutations, including R246Q and C321R, which are located in the LN or LEa domain of LAMB2 respectively, cause CNS with mild extrarenal features." (PMID 26156092, 2015). "Mutations in LAMB2 cause Pierson syndrome in humans, and affected individuals have severe congenital nephrotic syndrome." (PMID 25352829, 2014). "A complete laminin-521 network is the key for a functional GBM as mutations in LAMB2, the gene encoding the laminin β2 chain, cause Pierson syndrome in human beings." (PMID 25352829, 2014). "Mutations in the human LAMB2 gene cause Pierson syndrome, a severe glomerular kidney disease accompanied by ocular and neurological abnormalities." (PMID 22860131, 2012). "Mutations in the LAMB2 gene, encoding the laminin β2 chain, are associated with the Pierson's syndrome." (PMID 22693670, 2012). "Laminin β2 (LAMB2) is a crucial component present in the intestine, glomerular basement membrane, neuromuscular junctions, and various ocular structures, and it is associated with Pierson syndrome." (PMID 40625359, 2025). "Pathogenic variants in LAMB2 cause Pierson syndrome and nephrotic syndrome type 5." (PMID 36835142, 2023). "Pathological variants of LAMB2 were reported in a CMS patient with Pierson syndrome." (PMID 36835142, 2023). "Similarly to collagen, laminin retained 24–49% of their 14N contents across their nine identified isoforms of α1–5, β1 and 2, and γ1 and 3 (Mutations of LAMB2 that encodes Laminin β2 are associated with Pierson syndrome)." (PMID 32210336, 2020). "Mutations in LAMB2, encoding the basement membrane protein, laminin β2, are associated with an autosomal recessive disorder characterized by congenital nephrotic syndrome, ocular abnormalities, and neurodevelopmental delay (Pierson syndrome)." (PMID 31769495, 2020). "Mutations in the laminin β2 (LAMB2) gene are associated with Pierson syndrome." (PMID 28188379, 2017). "Mutations of the LAMB2 gene, which is located on chromosome 3, typically cause Pierson syndrome." (PMID 27004562, 2016). "Interestingly, nonsense and truncating mutations in LAMB2 are associated with Pierson syndrome, an autosomal recessive disorder characterized by congenital nephrotic syndrome, ocular abnormalities (commonly microcoria), muscular hypotonia, and neurological deficits." (PMID 31769495, 2020). "The causative genes linked to the Knobloch, Marfan, and Pierson syndromes are COL18A1, FBN1, and LAMB2, respectively." (PMID 40725504, 2025). "Mutations in LAMB2, which codes for Laminin subunit beta-2 protein that is a component of the GBM, cause Pierson syndrome (a type of CNS)." (PMID 41300747, 2025). "We recommend detailed ophthalmological examination in children with LAMB2 biallelic pathogenic variants, even though individuals with missense pathogenic variants may display variable phenotypes ranging from a milder variant of Pierson syndrome to an isolated CNS." (PMID 32467597, 2020). "Genetic testing for nephrotic syndrome revealed compound heterozygous missense mutations in LAMB2, the gene encoding laminin β2, a structural component of the GBM, previously implicated in Pierson syndrome (OMIM 609049)." (PMID 31769495, 2020). "LAMB2 knockout mice, which model is Pierson syndrome, show congenital albuminuria followed by podocyte foot process effacement, and they die at about 3 weeks of age with severe neuromuscular defects and nephrotic syndrome." (PMID 22693670, 2012). "Mutations in laminin genes have been identified in several human disorders: muscular dystrophy (LAMA2;), epidermolysis bullosa and Laryngo-onycho-cutaneous syndrome (LAMA3; LAMB3; LAMC2, and microcoria-congenital nephrosis syndrome (LAMB2)." (PMID 16522196, 2006).
Pierson syndrome (continued). "LAMB2-CMS was reported in a 20-year-old female with Pierson syndrome in 2009." (PMID 36835142, 2023). "However, promising results have been obtained recently from delivering the 800 kDa LM521 to the blood stream of LAMB2-null mice which rescues some aspects of Pierson syndrome." (PMID 34456976, 2021). "Mutations in LAMB2, encoding laminin β2, cause Pierson syndrome and occasionally milder nephropathy without extrarenal abnormalities." (PMID 33749661, 2021). "As to the three LAMB2-related SRNS, the age of onset was all younger than 1 years old, 2 of them with bilateral microcoria, presented with Pierson syndrome." (PMID 35755072, 2022).
nephrotic syndrome (14 papers, 2014 to 2025). A collection of symptoms that include severe edema, proteinuria, and hypoalbuminemia; it is indicative of renal dysfunction. "Conclusion: this report presents the variability of the renal, ocular and neurological phenotypes associated with LAMB2 mutations and underscores the importance of ophthalmologic examination in all children with unexplained renal insufficiency or nephrotic syndrome." (PMID 28188379, 2017). "Four patients (LAMB2, LAMA5 and PLCE1 variants) presented with nephrotic syndrome or nephrotic range proteinuria." (PMID 40003707, 2025). "Mutations in the NPHS1, NPHS2, LAMB2, and the WT1 genes are responsible for causing nephrotic syndrome (NS) in two third of the early onset cases." (PMID 30013592, 2018). "Transgenic podocyte-specific Lamβ1 expression in Lamb2−/− mice successfully increased LM-511 trimer deposition, eliminated nephrotic syndrome, and extended survival, highlighting a potential new therapeutic approach." (PMID 29435440, 2018). "The commonest genes associated with nephrotic syndrome differ at birth (NPHS1, NPHS2, WT1, LAMB2, PAX2, PLCE1), in childhood or adolescence (NPHS1, NPHS2, WT1, LAMB2, SMARCAL1, NUP107, TRPC6, PLCE1) and in adults (COL4A3-COL4A5, GLA, ACTN4, CD2AP, INF2, TRPC6)." (PMID 37578539, 2024). "Next-generation sequencing approaches have also identified LAMB2 missense mutations in congenital or childhood-onset nephrotic syndrome without apparent extrarenal abnormalities." (PMID 33749661, 2021). "For example, mutations of podocyte-associated genes account for approximately 30% of pediatric cases of steroid-resistant nephrotic syndrome with one of the four genes (NPHS1, NPHS2, WT1, and LAMB2) identified in 66% of nephrotic syndrome manifesting within the first year of life." (PMID 31049720, 2020). "The generation of LAMB2−/− mice has been useful in that they recapitulate Pierson syndrome, and develop congenital albuminuria, podocyte foot process effacement, and are non-viable from 3 weeks of age due to neuromuscular defects and nephrotic syndrome." (PMID 29435440, 2018). "Additional pathogenic variants were not identified in LAMB2 or in genes associated with early-onset nephrotic syndrome in this patient, but we suspect there is an additional pathogenic variant in LAMB2 that could not be identified." (PMID 33749661, 2021).
congenital nephrotic syndrome (12 papers, 2011 to 2025). "In our cohort, some of the genetic diagnoses were not expected based on the clinical phenotypes and age of onset as in the case of families 32 where LAMB2 variant was detected as a cause of the congenital nephrotic syndrome (CNS)." (PMID 40402239, 2025). "Mutations in the LAMB2 gene primarily manifest as steroid-resistant or congenital nephrotic syndrome, often accompanied by ocular abnormalities, suggesting a strong likelihood of this disease." (PMID 39416865, 2024). "Mutations in the LAMB2 gene disrupt the synthesis or function of the laminin α5β2γ1 (LM-521) isoform, resulting in Pierson syndrome, which is characterized by congenital nephrotic syndrome alongside eye and neurological defects." (PMID 39416865, 2024). "Mutations in the LAMB2 were also found in patients with congenital nephrotic syndrome, and LAMB2 mutations were reported to result in loss of laminin-β2 expression in the kidney." (PMID 22693670, 2012). "LAMB2 gene mutations are associated with Pierson syndrome, an autosomal recessive syndrome characterized by congenital nephrotic syndrome with histologic lesions of diffuse mesangial sclerosis and ocular malformations (microcoria, abnormal lens with cataracts, and retinal abnormalities)." (PMID 21904677, 2011). "Three genes were associated with congenital nephrotic syndrome: NPHS1 (2/2 families), LAMB2 (1/1 family) and COL4 A3 (1/1 family)." (PMID 40402239, 2025). "Most of the genes commonly associated with congenital nephrotic syndrome have reported ocular manifestations (NPHS1, NPHS2, WT1, LAMB2, PAX2, PLCE1)." (PMID 37578539, 2024). "Surprisingly, we found concurrent mutations in both LAMB2 and NPHP1 genes, for the first time in a child with congenital nephrotic syndrome." (PMID 27004562, 2016). "The LAMB2 gene mutation was initially identified by Pierson in 1963 as a condition affecting both the kidneys and eyes, characterized by congenital nephrotic syndrome and non-reactive small pupils." (PMID 39416865, 2024). "LAMB2 mutations have also been found in patients with congenital nephrotic syndrome and either no or less severe ocular abnormalities." (PMID 21904677, 2011).
renal failure (6 papers, 2009 to 2025). "In patients with LAMB2 variants, all patients with CNS developed kidney failure at a median age of 1.0 month." (PMID 40095038, 2025). "This is likely due to the short life span of patients with truncating LAMB2 mutations, as renal failure usually causes death within the first year of life." (PMID 19251977, 2009). "The patient in our case did not develop corticomedullary cysts in the kidneys and experienced renal failure soon after birth, suggesting that the LAMB2 mutations but not the NPHP1 mutations played a decisive role in renal failure in this case." (PMID 27004562, 2016). "In contrast, our case showed novel non-truncating compound heterozygous mutations of the LAMB2 gene associated with CNS and renal failure." (PMID 27004562, 2016).
congenital myasthenic syndrome (5 papers, 2009 to 2019). Congenital myasthenic syndrome (CMS) is a group of genetic disorders of impaired neuromuscular transmission at the motor endplate characterized by fatigable muscle weakness. "Maselli’s case study of congenital myasthenic syndrome (CMS) caused by mutations in the LAMB2 gene indicates that LAMB2 plays an important role in the development of neuromuscular junctions in humans." (PMID 31921022, 2019). "We describe a severe form of congenital myasthenic syndrome (CMS) associated with congenital nephrosis and ocular malformations caused by two truncating mutations in the gene encoding the laminin β2 subunit (LAMB2)." (PMID 19251977, 2009).
focal segmental glomerulosclerosis (4 papers, 2015 to 2025). A renal disorder characterized by sclerotic lesions in the glomeruli. "Ocular abnormalities other than microcoria were found in two patients with PS with onset of nephrotic proteinuria beyond 1 year of age and focal segmental glomerulosclerosis who had homozygous or compound heterozygous LAMB2 truncated variants." (PMID 33982833, 2021). "Two patients (LAMB2 and LAMA5 variants) were diagnosed with focal segmental glomerulosclerosis." (PMID 40003707, 2025).
glomerulopathy (3 papers, 2020 to 2024). "Individuals with LAMB2-associated glomerulopathy need to be managed by multidisciplinary team composed of pediatric optalmologist, clinical geneticist, pediatric neurologist and rehabilitation team." (PMID 32467597, 2020).